DTX1 (deltex E3 ubiquitin ligase 1)
Description:
E3 ubiquitin-protein ligase that mediates ubiquitination and proteasomal degradation of MEKK1, thereby modulating signaling pathways involved in cell fate determination (By similarity). Regulates the Notch signaling pathway, acting predominantly as a positive regulator but functioning as a context-dependent negative regulator in specific developmental or cellular settings. Mediates the antineural activity of Notch signaling, likely by inhibiting transcriptional activation mediated by MATCH1. Negatively regulates Notch signaling by controlling the activity of PIP4K2C, a lipid kinase that promotes recycling of Notch receptors from RAB4A-positive endosomes to the cell surface. Participates in several developmental and immune processes, including neurogenesis, lymphogenesis, and myogenesis. Influences lymphocyte differentiation by promoting B-cell development at the expense of T-cell development, suggesting functional antagonism of NOTCH1 in this context. Also promotes degradation of PRKCQ via the endosome-lysosome pathway, contributing to PKCtheta downregulation during T-cell anergy. In addition, facilitates differentiation of Th17 cells by inducing expression and DNA-binding activity of RORgT.
Synonyms: hDx-1; RNF140
Tractability: Small molecule: a structure with a bound ligand is known. PROTAC: UniProt records ubiquitination sites on it; ubiquitination databases record sites on it.
Gene: Protein-coding gene on chromosome 12 (113,056,710 to 113,098,028, forward strand). Ensembl gene ENSG00000135144.
Subcellular location: Cytoplasm; Nucleus; Endosome
Subcellular location (Human Protein Atlas): Cytosol; Nucleoplasm; Nuclear bodies
Pathways (Reactome):
Signal Transduction: Activated NOTCH1 Transmits Signal to the Nucleus
Gene Ontology:
Molecular function: Notch binding; protein binding; ubiquitin protein ligase binding; transcription coactivator activity; ubiquitin protein ligase activity; zinc ion binding
Biological process: negative regulation of neuron differentiation; regulation of Notch signaling pathway; cell surface receptor signaling pathway; DNA-templated transcription; Notch signaling pathway; protein ubiquitination; transcription by RNA polymerase II; positive regulation of DNA-templated transcription
Cellular component: cytosol; nuclear body; nucleoplasm; cytoplasm; endosome; nucleus
Genetic constraint (gnomAD): Loss-of-function variants: 26 observed, 48.72 expected, observed/expected ratio (o/e) 0.53, 90% interval 0.39 to 0.74. The upper end of that interval is the gene's LOEUF score, 0.74, which puts it in group 3 of 6, group 1 being the genes least tolerant of losing a copy. Missense variants: 703 observed, 804.21 expected, observed/expected ratio (o/e) 0.87, 90% interval 0.82 to 0.93. Synonymous variants: 398 observed, 350.64 expected, observed/expected ratio (o/e) 1.14, 90% interval 1.04 to 1.23.
Homologues: Orthologues: chimpanzee DTX1 (100% identical), macaque DTX1 (99% identical), dog DTX1 (97% identical), mouse Dtx1 (97% identical), rat Dtx1 (97% identical), pig DTX1 (96% identical), tropical clawed frog dtx1 (78% identical), zebrafish DTX1 (40% identical). Paralogues in human: DTX4 (62% identical), DTX2 (46% identical), DTX3L (19% identical), DTX3 (14% identical).
Diseases named in the same sentence as DTX1 in open-access papers:
DTX1 is named in the same sentence as 42 diseases in open-access papers, as found by Europe PMC text mining. Sharing a sentence is not in itself a finding about the gene and the disease. The quoted sentences say what the papers report.
glioma (6 papers, 2013 to 2025). A benign or malignant brain and spinal cord tumor that arises from glial cells (astrocytes, oligodendrocytes, ependymal cells). "DTX1 has been linked to invasiveness in osteosarcoma, however, its role in glioma remains elusive." (PMID 23451269, 2013). "It was seen that the interference of DTX1 in glioma cells can activate the Notch signaling pathway and then produce a series of regulatory effects." (PMID 33014056, 2020). "Altogether, we found DTX1 to be expressed in glioma biopsies and cell lines both at the transcript and protein level." (PMID 23451269, 2013). "Two independent probes detecting DTX1 mRNA (1559618_at and 227336_at, Affymetrix) confirmed DTX1 expression in all glioma samples analyzed." (PMID 23451269, 2013). "To further investigate the role of DTX1, we generated cell lines over-expressing DTX1 (pcDNA3-DTX1-myc) and glioma cells with reduced levels of DTX1 through shRNA interference (pLKO.1-shRNA-DTX1)." (PMID 23451269, 2013). "We found expression of DTX1 protein at varying levels in all glioma cell lines, tumor biopsies and ex vivo cell lines analyzed by immunoblotting, confirming the transcript analysis." (PMID 23451269, 2013). "We therefore analyzed the levels of Snail1 in our glioma cell lines and found a positive correlation with DTX1." (PMID 23451269, 2013). "In both glioma cell lines analyzed, down-regulation of DTX1 reduced the levels of phosphorylated Erk (p-Erk)." (PMID 23451269, 2013). "This is in accordance with our in vitro data and identifies DTX1 as an oncogenic factor in high grade gliomas." (PMID 23451269, 2013). "However, a study showed that DTX1 is highly expressed in many glioma samples and glioma cell lines and is necessary for inducing glioma cell proliferation." (PMID 26714454, 2015). "Taken together, these results show a significantly reduced aggressiveness of established glioma cells with down regulated DTX1 as shown by the reduced ability to give rise to cell colonies or spheres in all assays performed, an effect we found to be insensitive to miR-21 inhibition." (PMID 23451269, 2013). "DTX1 increased tumor cell aggressiveness, seen by elevated clonogenicity, increased the migratory and invasive potential of established glioma cells and induced several signaling pathways protecting tumor cells from apoptosis and stimulating survival and proliferation." (PMID 23451269, 2013). "The clonogenic and growth potential of established glioma cells correlated with DTX1 levels." (PMID 23451269, 2013). "In this study we demonstrated an oncogenic role of DTX1 in high grade glioma cell lines." (PMID 23451269, 2013). "In this study we provide evidence that DTX1 has an oncogenic role in high grade glioma cell lines." (PMID 23451269, 2013). "The Notch pathway (via NOTCH1, HES1, DTX1) and its interaction with TRIM8 and STAT3 signaling represent another axis for potential intervention, particularly in glioma stem-like cells." (PMID 41179304, 2025). "We analyzed the effect of DTX1 on the expression level of EGF receptor (EGFR), a receptor tyrosine kinase frequently over-expressed in gliomas." (PMID 23451269, 2013). "We analyzed Deltex1 (DTX1) expression both at the transcript and the protein level in tumor biopsies and glioma-derived cell lines to confirm its presence in gliomas." (PMID 23451269, 2013). "In the EGFR-expressing glioma cell line LN18, DTX1 over-expression increased EGFR protein levels." (PMID 23451269, 2013). "DTX1 aggravates several of these mechanisms in U373 and LN18 glioma cells." (PMID 23451269, 2013). "Although elevated average levels of DTX1 expression were found in glioma samples, this difference was not significant (p = 0.094)." (PMID 23451269, 2013). "In mice, three new ligands to the Notch receptor family have been identified which signal specifically through the DTX1 pathway independently of RBPJκ and MAML1 and one of these ligands (DNER) has been implicated in non-canonical regulation of glioma inducing cells." (PMID 23451269, 2013).
lymphoma (6 papers, 2012 to 2022). A malignant (clonal) proliferation of B- lymphocytes or T- lymphocytes which involves the lymph nodes, bone marrow and/or extranodal sites. "NOTCH2, regulated by DTX1 protein, has been found recurrently mutated in several types of lymphoma, including splenic marginal zone lymphoma, DLBCL and FL." (PMID 30802265, 2019). "Consistent with this, and as an example, we observed that the levels of expression of the canonical ICN1 target genes Hes1, Dtx1, and Ptcra are quite similar in the lymphoma cells from both mouse models." (PMID 35895495, 2022). "We further explored whether overexpression of DTX1 increased the sensitivity of T lymphoma to death receptor-induced cell death by targeting c-FLIPL for degradation." (PMID 29374180, 2018). "Thus, DTX1 promotes DR-induced cell death in normal T cells and in T lymphoma." (PMID 29374180, 2018). "Here, we found that DTX1 enhances c-FLIPL downregulation in gastric cancer cells and lymphomas via an endosome-lysosomal pathway." (PMID 29374180, 2018).
osteosarcoma (6 papers, 2013 to 2024). A usually aggressive malignant bone-forming mesenchymal neoplasm, predominantly affecting adolescents and young adults. "Human Deltex (DTX1) was also shown to regulate NOTCH1/HES1 signaling negatively in osteosarcoma cells." (PMID 38900140, 2024). "According to Zhang and colleagues, HES1 can directly downregulate Dtx1, which is acting as a negative regulator of Notch1 signaling, through degradation of the intracellular domain of Notch1 in osteosarcoma." (PMID 28122586, 2017). "This is the first report that has demonstrated that DTX1 blocks HNSCC migration, which is in agreement with recently published data suggesting that DTX1 blocks osteosarcoma invasiveness." (PMID 28146432, 2017). "On the other hand, recent data suggest that DTX1 may play a role in inhibition of invasion in osteosarcoma." (PMID 28146432, 2017). "In mammalian osteosarcoma cells, the direct binding of HES1 (Hairy/enhancer of split 1) to these N-boxes within the DTX1 promoter also inhibits DTX1 transcription and leads to an increase in cell invasion." (PMID 35204725, 2022).
breast cancer (5 papers, 2012 to 2025). A primary or metastatic malignant neoplasm involving the breast. "Lower levels of DTX1 could promote breast cancer (BC) cell proliferation and migration and are associated with advanced BC." (PMID 36681855, 2023). "For example, the better prognosis of early breast cancer patients with low DTX1 expression levels points in this direction." (PMID 23451269, 2013). "To assess whether this finding was conferrable to other cancers, we analyzed a data set of early breast cancer samples for the correlation of DTX1 expression levels and patient survival." (PMID 23451269, 2013). "Finally, low DTX1 expression levels correlate with longer survival in GBM and breast cancer patients." (PMID 23451269, 2013).
gastric cancer (5 papers, 2018 to 2022). A primary or metastatic malignant neoplasm involving the stomach. "Increased expression of c-FLIP in DTX1-deficient cells suggests that DTX1 downregulation confers resistance to TRAIL-induced apoptosis in gastric cancer cells." (PMID 29374180, 2018). "The ubiquitin E3 ligase DELTEX1 (DTX1) is specifically downregulated in gastric cancer tissues, and expression of DTX1 is linked to better prognoses and survival in gastric cancer." (PMID 29374180, 2018). "Furthermore, DTX1 plays a tumor-suppressive role and is negatively associated with gastric cancer progression." (PMID 34513839, 2021). "We propose that reagents that can stimulate the expression of DTX1 may enhance the susceptibility of gastric cancer to TRAIL treatment." (PMID 29374180, 2018). "In gastric cancer cells, DTX1 primarily promotes the degradation of cellular FADD-like IL-1β-converting enzyme-inhibitory protein (c-FLIP) in the lysosomal pathway and enhances TNF-related apoptosis-inducing ligand (TRAIL)-induced cell death." (PMID 34513839, 2021). "In gastric cancer, DTX1 was reported specifically down-regulated and promoted cellular FLICE inhibitory protein (c-FLIP), as its E3 ligase substrate, to degrade through the endosome-lysosomal pathway." (PMID 33403043, 2021). "We have also demonstrated that gastric cancer cells, which are relatively resistant to TRAIL treatment, become susceptible to TRAIL-induced cell death in the presence of DTX1." (PMID 29374180, 2018). "In the present study, we show that DTX1 is specifically downregulated in gastric cancer and is critical for the resistance of gastric cancer cells to TRAIL-induced cell death." (PMID 29374180, 2018). "Re-introduction of DTX1 into gastric cancer cells increased TRAIL-induced apoptosis and also reduced c-FLIP." (PMID 29374180, 2018). "Together, our results suggest that increased DTX1 enhances TRAIL-triggered apoptosis in gastric cancer cells partly by downregulation of c-FLIP." (PMID 29374180, 2018). "DTX1 was downregulated in most of our gastric cancer samples." (PMID 29374180, 2018). "Here, we show that DTX1 is an E3 ligase for c-FLIP in gastric cancer cells." (PMID 29374180, 2018). "Consequently, DTX1 expression enhanced the susceptibility of gastric cancer cells to TRAIL-induced apoptosis, whereas DTX1 downregulation increased the resistance to TRAIL-triggered cell death." (PMID 29374180, 2018). "Therefore, DTX1 is downregulated in gastric cancer tissues and DTX1 expression is negatively correlated with gastric cancer progression." (PMID 29374180, 2018). "Our results suggest that a combination of TRAIL with compounds that increase DTX1 expression could be a new approach for gastric cancer therapy." (PMID 29374180, 2018). "In addition, a treatment that increased DTX1 expression also sensitized gastric cancer to TRAIL treatment." (PMID 29374180, 2018). "Here, we report a new finding that DTX1 is an E3 ligase for c-FLIP in gastric cancer cells." (PMID 29374180, 2018). "The involvement of DTX1 in c-FLIP degradation is not limited to gastric cancer cells." (PMID 29374180, 2018). "In another gastric cancer cell line, SNU-16, DTX1 expression also reduced the protein levels of FLIPL and c-FLIPS, with a concomitant increase in TRAIL-induced cell death." (PMID 29374180, 2018). "Our results reveal a tumor-suppressive role for DTX1 and suggest a new approach to increasing TRAIL efficacy by raising DTX1 levels in gastric cancer therapy." (PMID 29374180, 2018). "Overexpression of DTX1 sensitized gastric cancer cells to TRAIL-induced apoptosis, whereas DTX1-knockdown attenuated apoptosis induction." (PMID 29374180, 2018). "In summary, we identify DTX1, but not CBL or ITCH, as the E3 ligase regulating c-FLIP protein stability in gastric cancer cells." (PMID 29374180, 2018).
glioblastoma (5 papers, 2013 to 2021). The most malignant astrocytic tumor (WHO grade IV). "The migration and invasion of Glioblastoma (GBM) cells were positively associated with expressions of DTX1." (PMID 33403043, 2021). "Overexpression of DTX1 increases the clonal ability, growth potential, and invasiveness of glioblastoma cells." (PMID 34513839, 2021). "DTX1 is upregulated in thymic tumors and in glioblastoma, and it inhibits osteoblastoma cell invasion." (PMID 28146432, 2017). "The alternative Notch pathway via DTX1 appears to be an oncogenic factor in glioblastoma and these findings offer new potential therapeutic targets." (PMID 23451269, 2013). "Patients with low expression of DTX1 have a longer survival and a better prognosis of glioblastoma." (PMID 34513839, 2021). "While the NOTCH pathway is activated in many cancer types, DTX1 is seen to be downregulated in osteoblastoma and HNSCC, while it is upregulated in glioblastoma." (PMID 28146432, 2017). "We show that the alternative or non-canonical Notch pathway functioning through Deltex1 (DTX1) mediates key features of glioblastoma cell aggressiveness." (PMID 23451269, 2013). "In addition, induction of DNER by the histone deacetylase inhibitor trichostatin A (TSA) has been shown to reduce the tumorigenicity and cell differentiation of glioblastoma-derived neurosphere lines via the DTX1-mediated non-canonical Notch signaling pathway." (PMID 34513839, 2021). "To elucidate the role of DTX1 in patients, we analyzed the data publicly available at the REMBRANDT database (REpository of Molecular BRAin Neoplasia DaTa, NCI, NIH, USA) to determine if our in vitro findings could be brought forward to glioblastoma behavior in patients." (PMID 23451269, 2013).
leukemia (3 papers, 2020 to 2021). A malignant (clonal) hematologic disorder, involving hematopoietic stem cells and characterized by the presence of primitive or atypical myeloid or lymphoid cells in the bone marrow and the blood. "Inhibition of the NOTCH1 pathway in ΔE-NOTCH1 T-leukemia samples was confirmed by Western blot, showing that in DBZ- vs. DMSO-treated cells, there was a strong downregulation in ICN1 protein levels, with Dtx1, a direct target of NOTCH1, also significantly decreased." (PMID 32708470, 2020).
B cell lymphomas (2 papers, 2020 to 2023). "Mutational profiling using a custom panel of 168 genes associated with aggressive B-cell lymphomas confirmed mutations in ACTB, ARID1B, DUSP2, DTX1, HLA-B, PTEN, and TNFRSF14." (PMID 36975733, 2023).
diffuse large B-cell lymphoma (2 papers, 2021). "Missense or nonsilent DTX1 mutations have been reported in splenic marginal zone lymphomas and in Chinese patients with primary and recurrent diffuse large B-cell lymphomas (DLBCLs)." (PMID 34513839, 2021).
non-small cell lung carcinoma (2 papers, 2021 to 2022). A group of at least three distinct histological types of lung cancer, including non-small cell squamous cell carcinoma, adenocarcinoma, and large cell carcinoma. "DTX1 is a regulator of the Notch signaling pathway and acts as an E3 ubiquitin ligase that can repress Notch gene expression and inhibit early-stage non-small cell lung carcinoma growth." (PMID 35060926, 2022).
acute lymphoblastic leukemia (1 paper, 2017). Leukemia with an acute onset, characterized by the presence of lymphoblasts in the bone marrow and the peripheral blood. "Moreover, multiple DTX1 polymorphisms were found in non-small cell lung and B-cell precursor acute lymphoblastic leukemia patients, which most likely associate with inactivation of DTX1 and further NOTCH activation in these cancers." (PMID 28146432, 2017).
brain tumors (1 paper, 2015). "In conclusion, our results provide information for a clearer understanding of the role of Dtx1 and the mechanism underlying Notch signaling in neural development and the progression of brain tumors." (PMID 26714454, 2015). "We analyzed DTX1 expression in several types of brain tumor cell line (T98G, U-87 MG, A172, Hs 683, D341 Med, M059K, CHP-212, and H4), which displayed low DTX1 expression levels (unpublished observation)." (PMID 26714454, 2015). "By contrast, based on an analysis of the Cancer Genome Anatomy Project and Gene Expression Omnibus expression databases, we found that DTX1 is expressed at low levels in brain tumors." (PMID 26714454, 2015). "On the basis of the results of our in vivo study of the zebrafish developing nervous system showing that Dtx1 induces neural differentiation and is not involved in proliferation and apoptosis, we suggest that Dtx1/DTX1 does not play an inductive role in the progression of at least some brain tumors." (PMID 26714454, 2015).
Cerebral arteriovenous malformation (1 paper, 2022). "METTL3 plays a similar role in cerebral arteriovenous malformation, and deletion of METTL3 in ECs significantly affects angiogenesis by reducing heterodimeric Notch E3 ubiquitin ligase formed by DTX1 and DTX3L." (PMID 35001873, 2022).
colitis (1 paper, 2015). Inflammation of the colon. "In contrast, the co-administration of Dtx1−/− tTregs only weakly reduced the colitis-associated pathogenesis, suggesting that the absence of DTX1 greatly diminished the suppressive activities of tTregs in vivo." (PMID 25695215, 2015). "Consistent with normal levels of Foxp3 in the recovered Tregs, Hif1a-knockout re-established the ability of Dtx1−/− tTregs to repress CD4+CD25− T cell-induced colitis in Rag1−/− mice as determined by colitis score readout, body weight loss and intestinal morphology." (PMID 25695215, 2015). "We examined whether Dtx1−/− Tregs behaved differently from WT Tregs in the inflammatory mucosal environments where colitis and allergic airway responses take place." (PMID 25695215, 2015).